LONRF1 (LON peptidase N-terminal domain and ring finger 1)
Synonyms: RNF191; FLJ23749
Tractability: Antibody: the Human Protein Atlas places it where antibodies can reach. PROTAC: ubiquitination databases record sites on it.
Gene: Protein-coding gene on chromosome 8 (12,721,906 to 12,756,073, reverse strand). Ensembl gene ENSG00000154359.
Subcellular location (Human Protein Atlas): Cytosol; Plasma membrane; Centrosome
Pathways (Reactome):
Immune System: Antigen processing: Ubiquitination & Proteasome degradation
Gene Ontology:
Molecular function: protein binding; ubiquitin protein ligase activity; metal ion binding
Cellular component: cytosol
Genetic constraint (gnomAD): Loss-of-function variants: 31 observed, 63.86 expected, observed/expected ratio (o/e) 0.49, 90% interval 0.36 to 0.65. The synonymous counts are far from expectation, so gnomAD's model fits this gene poorly and the ratio says little. Missense variants: 976 observed, 786.17 expected, observed/expected ratio (o/e) 1.24, 90% interval 1.18 to 1.31. Synonymous variants: 490 observed, 318.76 expected, observed/expected ratio (o/e) 1.54, 90% interval 1.43 to 1.66.
Homologues: Orthologues: chimpanzee LONRF1 (99% identical), macaque LONRF1 (98% identical), dog LONRF1 (92% identical), pig LONRF1 (91% identical), rat Lonrf1 (88% identical), mouse Lonrf1 (87% identical), rabbit LONRF1 (51% identical), zebrafish lonrf1 (48% identical), Drosophila melanogaster CG32369 (28% identical), Caenorhabditis elegans T02C1.1 (6% identical). Paralogues in human: LONRF2 (39% identical), LONRF3 (35% identical).
Diseases named in the same sentence as LONRF1 in open-access papers:
LONRF1 is named in the same sentence as 1 disease in open-access papers, as found by Europe PMC text mining. Sharing a sentence is not in itself a finding about the gene and the disease. The quoted sentences say what the papers report.
myopia (1 paper, 2024). "The overall categories in the differentially expressed genes during myopia onset and progression share only three genes in retina: LONRF1, RAD54L2 and DUSP4." (PMID 39028695, 2024).